ACHE (acetylcholinesterase (Yt blood group))
Diseases named in the same sentence as ACHE in open-access papers (continued):
Sharing a sentence is not in itself a finding about the gene and the disease.
neurodegenerative disease (continued). "Particularly, the inhibition effect on AChE (IC50: 16.116 μg/mL) and BChE (IC50: 8.556 μg/mL) suggests the potential therapeutic application of MLs in the treatment of neurodegenerative diseases such as Alzheimer's." (PMID 40351366, 2025). "The elevated content of tocopherols, tocotrienols, and amino acids, correlated selectively with anti-AChE and/or anti-BuChE activity, underscores the significance of PPF in dietary approaches for treating neurodegenerative diseases." (PMID 39061853, 2024). "Moreover, beyond the currently used donepezil, galantamine, and rivastigmine, research is anticipated on pharmacotherapeutic targets that possess AChE-inhibiting properties and could improve gait and reduce falls in patients with neurodegenerative diseases, thereby enhancing cholinergic function." (PMID 39666629, 2024). "AChE activity was evaluated in seven patients with familial OPCA and compared with the enzyme activity values in patients with other neurodegenerative diseases such as AD and PD." (PMID 34502198, 2021). "Therefore, in further studies, it is necessary to analyze in detail the separated components of Bitis snake venom and to determine which substance can be attributed to stimulatory or inhibitory effects on the AChE activity and could have potential in the treatment of neurodegenerative diseases." (PMID 33922392, 2021). "The inhibitory ability of the phenylethanoid against several enzymes implied in neurodegenerative diseases (tyrosinase, MAO-A, and AChE) was analyzed in vitro." (PMID 33266151, 2020). "Acetylcholinesterase (AChE) and monoamine oxidase (MAO) are enzymatic targets for the search of new drugs for the treatment of neurodegenerative diseases." (PMID 32784526, 2020). "The in vitro neuroprotective potential was evaluated through the analysis of the effect of the phenylethanoid against several enzymes implied in neurodegenerative diseases: tyrosinase, MAO-A, and AChE." (PMID 33266151, 2020). "The improved AChE inhibition observed in the nanoformulation of LOEO provides compelling evidence for developing more effective and targeted treatments for neurodegenerative diseases, offering a promising avenue for future research and pharmaceutical applications." (PMID 40286153, 2025). "Thus, the inhibition of AChE, BChE, and TYR is considered an important strategy in the management of neurodegenerative diseases." (PMID 39202972, 2024). "In particular, compounds targeting AChE and MAO-B could be useful tools for the treatment of neurodegenerative diseases." (PMID 37570828, 2023). "Furthermore, we employed molecular docking and molecular dynamics studies of the phenolic compounds with the proteins AChE, BChE, and BACE-1 in order to evaluate the binding characteristics and identify potent anti-amyloid agents against the neurodegenerative diseases such as AD." (PMID 31319560, 2019).
neurological disorders (69 papers, 2013 to 2025). "Butyrylcholinesterase (BChE) and acetylcholinesterase (AChE) hydrolyze butyrylcholine and acetylcholine neurotransmitters, respectively, reducing nerve transmission to the brain and causing neurological disorders." (PMID 41393958, 2025). "Inhibition of key enzymes implicated in neurological disorders, including AChE, BChE, beta-secretase and monoamine oxidase, has been identified as a promising approach towards developing neurotherapeutic agents." (PMID 40893584, 2025). "OPs are AChE inhibitors that impair the cholinergic system and interrupt axonal transport and mitochondrial function, thereby triggering neurological disorders, e.g., memory loss." (PMID 37626550, 2023). "For example, AChE is an enzyme responsible for lowering the level of acetylcholine in the brain, which eventually causes neurological disorders." (PMID 32392806, 2020). "The inhibitory activity of the cranberry extract against cyclooxygenase-1 (COX-1) and cyclooxygenase-2 (COX-2), which are mediators of inflammation, and acetylcholinesterase (AChE), which is responsible for acetylcholine breakdown and potentially linked to neurological disorders, was analyzed." (PMID 38067623, 2023). "Some of the substances could cause neurological disorders, for example, the inhibition of the activity of acetylcholinesterase (AChE), which is an important enzyme to regulate synaptic transmission." (PMID 35807578, 2022). "Therefore, many AChE inhibitors are clinically used in the treatment of neurological diseases associated with cholinergic deficits, including AD in particular." (PMID 27023569, 2016). "Both OPs and CMs inhibit acetylcholinesterase (AChE), a key enzyme in neural signaling, leading to severe health effects, including neurological disorders, respiratory failure, and potentially fatal outcomes." (PMID 40238274, 2025). "The AChE inhibition increases the levels of Ach; thus, AChE inhibition is considered a useful therapeutic approach to treat neurological disorders like AD." (PMID 40868857, 2025). "Due to its dual inhibition of AChE and BChE activities, hesperidin from Astragalus crenatus holds promise for the development of novel therapeutics aimed at neurological disorders, particularly AD." (PMID 38543134, 2024). "Natural products are extensively researched for their potential as AChE inhibitors, given their potential utility in treating various neurological disorders." (PMID 39065009, 2024). "The relationship between the inhibition of the AChE enzyme and neurological diseases has been the subject of extensive scientific research." (PMID 37987444, 2023). "A known challenge to all inhibitors for neurological diseases such as AD is the ability to cross the blood–brain barrier to inhibit AChE." (PMID 36937207, 2022). "Cd also significantly inhibited acetylcholinesterase (AChE) activity in the brain tissue of zebrafish and Lepisosteus oculatus and induced neurological disorders." (PMID 36287901, 2022). "The alcoholic and aqueous extracts of plants used in the traditional medicine of Navarra for neurological diseases were screened for AChE inhibition." (PMID 36296692, 2022). "Considering the side effects of current drugs for AChE inhibition, it is necessary to screen natural AChE inhibitors with fewer toxic side effects to treat neurological diseases." (PMID 36388527, 2022). "The experimental system was an amperometric biosensor with an oxidase (tyrosinase) and a neural esterase (AChE) co-immobilized on the working electrode of a commercially available SPE array to detect markers of neurological disease." (PMID 34821676, 2021). "For that reason, significant research has been devoted to developing amperometric biosensors that measure markers of neurological disease processes that inhibit neural esterases, such as acetylcholinesterase (AChE)." (PMID 34821676, 2021).
neurological disorders (continued). "The related enzyme butyrylcholinesterase (BChE) is also involved in the regulation of the cholinergic system as a backup to AChE in hydrolyzing the neurotransmitter acetylcholine (ACh) in neurological disorders." (PMID 34832929, 2021). "The results indeed demonstrate an anticholinergic activity of the tested essential oils, and therefore their a potential value for the the treatment of neurological disorders, acting as AChE and BuChE inhibitors." (PMID 32486467, 2020). "In CR, 52 AD-related target proteins were validated to bind with 25 active ingredients, including ACHE, APP, BCHE, BCL2, BAX, CASP3, and CASP7, and are implicated in cell apoptosis and vascular and nervous system diseases." (PMID 32802132, 2020). "In the treatment of neurological disorders, potential inhibitors of acetylcholinesterase (AChE) and butyrylesterase (BChE) enzymes are of prime importance." (PMID 29295712, 2018). "In that way, AChE inhibitors play an important role in the nervous system disorders, owing to their potential as pharmacological and toxicological agents." (PMID 26400617, 2015). "There is a dire need to explore in detail the underlying mechanism by which natural nutraceutical like Vitamin D3 (VD) decreases acetylcholine esterase (AChE) activity, along with its anti-inflammatory, antioxidant, and neuroprotective benefits in neurological disorders." (PMID 40668334, 2025). "Many plants possess antioxidant and anti-inflammatory properties while also affecting improvement in the ACh levels or limiting AChE in the brain, which may aid in treating AD and other neurological disorders." (PMID 40004981, 2025). "Indeed, coumarins have shown very promising activity in the treatment of neurological disorders, like AD and PD, for their ability to selectively target enzymes involved in neurotransmitter metabolisms, such as AChE and MAO-B, at nanomolar concentrations." (PMID 38440776, 2024). "Although the inhibition of AChE has been extensively studied as a symptomatic treatment in neurological diseases, less attention has been paid to its sister enzyme, butyrylcholinesterase (BChE), that co-regulates the metabolism of the neurotransmitter acetylcholine." (PMID 37047044, 2023). "Furthermore, carvacrol shows AChE inhibitory potential, which helps to treat neurological disorders such as AD." (PMID 37047044, 2023). "As a consequence, the nanoreactors significantly inhibited the decline in AChE activity in the brain, which may account for long-term and delayed neurological disorders." (PMID 37550745, 2023). "The beneficial effects of anethole in neurological disorders may also be due to its inhibitory properties on acetylcholinesterase (AChE)." (PMID 37972114, 2023). "Being AChE inhibitors, tacrine and its analogues work by increasing the availability of acetylcholine in central cholinergic synapses and are hence considered as the most promising medications now available for the treatment of neurological diseases like AD." (PMID 36035218, 2022). "Our results suggest that the alkaloids 1–4 could be used as reversible AChE inhibitors in the treatment of neurological disorder manifestations." (PMID 35630611, 2022). "Due to inhibition of AChE, the levels of acetylcholine, a neurotransmitter, increases in the brain thereby improving cholinergic functions in AD patients and mitigate the symptoms of neurological disorders." (PMID 35239683, 2022). "The venom of P. bundokalbo contains compounds thatdemonstrate neuroactivity and anti-AChE activities invitro, which could comprise possible therapeutic leads for thedevelopment of cholinergic compounds against neurological diseases." (PMID 34249120, 2021). "A novel, integrated experimental and modeling framework was applied to an inhibition-based bi-enzyme (IBE) electrochemical biosensor to detect acetylcholinesterase (AChE) inhibitors that may trigger neurological diseases." (PMID 34821676, 2021).
neurological disorders (continued). "Our results suggest that 5-N-methylmaytenine and stepharine could be used as reversible AChE inhibitors in the treatment of neurological disorder manifestations, as well as candidate immunomodulatory agents in the inflammatory disease context." (PMID 32991579, 2020). "Therefore, prolonging the half‐life of Ach by the use of cholinesterase inhibitors which are responsible for the hydrolysis of AChE and terminating its function is currently used as a treatment approach of neurological disorders." (PMID 30510739, 2018). "Furthermore, based on the current review, it is concluded that N. sativa seed and main constituents through inhibition of AChE activity and increasing the GABAergic tone and particularly antioxidant effects improved nervous system diseases." (PMID 26604923, 2015). "Similarly, the capacity for inhibition against clinically important enzymes involved in major pathologies, including neurological disorders (acetylcholinesterase, AChE; butyrylcholinesterase, BChE), skin conditions (tyrosinase), and diabetes (α-amylase), were also examined." (PMID 34483902, 2021). "An increase in the concentration of AChE in the brain results in the degradation of Ach, eventually reducing the ACh receptors and then inducing undesirable effect on cholinergic neurotransmission, and also results in impairment of cognitive function as well as other neurological disorders." (PMID 33994883, 2021). "Several key enzymes, such as acetylcholinesterase (AChE), beta-secretase (BACE1), tau kinases, monoamine oxidase, caspases, and cyclooxygenase-2, reportedly play significant roles in the development of neurological disorders." (PMID 40429850, 2025). "The antioxidant activity and the ability to inhibit CNS enzymes such as AChE, MAO, and TYR, could explain the traditional use of J. glutinosa in treating disorders of the nervous system." (PMID 40141177, 2025). "These noncholinergic functions of AChE may be crucial in neurological disorders, and tacrine may be able to influence them positively." (PMID 36035218, 2022).
cancer (57 papers, 2012 to 2025). A tumor composed of atypical neoplastic, often pleomorphic cells that invade other tissues. "In this study, we aimed to determine the association between cancer and the blood level of the (AChE)." (PMID 38429330, 2024). "Since AChE has the potential to inhibit the proliferation of a wide range of cancer cells, this probe is expected to be a potential diagnostic and therapeutic tool for clinical diagnosis and pathological mechanistic studies of AChE-related diseases." (PMID 38731452, 2024). "In this study, we aimed to explore this public health problem and evaluate the association between impaired AChE and cancer." (PMID 38429330, 2024). "The natural compound β-mangostin has potential activities associated with cancer cell toxicity, inhibition of AChE and α-glucosidase, and Gram-positive antibacterial activity." (PMID 37593716, 2023). "On the basis of the results, it was determined that compound 3 featured a reactive profile and powerful anti-enzyme activity, making it a potential new therapeutic strategy against AChE and BChE-associated malignancies." (PMID 36226116, 2022). "Combined staining of AChE and the PCa cell marker Cytokeratin 19 (CK19) using double-immunofluorescence (IF) staining confirmed strong co-localization of CK19 with AChE, underlining the specificity of AChE expression in cancer cells." (PMID 33357230, 2020). "In light of these findings decreased AChE amount is associated with tumorigenesis and thus, studying its role in tumor microenvironment has potential implications in cancer diagnosis and therapy." (PMID 29371671, 2018). "ACh and AChE levels have also been associated with several other carcinomas like colon, prostate and breast." (PMID 29371671, 2018). "There was a significant statistical association between impaired (AChE) activity and cancer." (PMID 38429330, 2024). "We could hypothesize that in the initial cancer stages, initiated cells could have high AChE activity, diminishing the local ACh concentrations, causing both the inflammation and TAMs to increase for a long time and resulting in the appearance of tumors." (PMID 37760598, 2023). "Understanding how new Ru(II) complexes interact with ACHE and MMP-9 is crucial, as both enzymes are instrumental in cancer progression, ACHE through its role in cell signaling and proliferation, and MMP-9 in facilitating tumor invasion and metastasis." (PMID 40149886, 2025). "The presence of AChE in exosomes from serum, stem cells, and cancer cell lines has been verified using mass spectrometry and western blotting." (PMID 38711645, 2024). "The primary objective of this study is to assess the level of (AChE) in cancer patients and evaluate its potential application as a diagnostic biomarker and therapeutic target." (PMID 38429330, 2024). "Few published reports have explored the ability of AChE-enhancing agents/inhibitors to sensitize human cancer cells to the pro-apoptotic effects of chemotherapy." (PMID 38429330, 2024). "Inferential analysis revealed significantly impaired (AChE) activity among cancer patients compared to controls (53.4 ± 20.3% vs. 93.8 ± 8.8, p-value 0.001)." (PMID 38429330, 2024). "AChE expression in a variety of cancerous tissues is usually lower than that in paraneoplastic tissues, and it has a growth inhibitory effect on cancer cells." (PMID 38731452, 2024). "Univariate analysis compared individual cancers versus controls, then compared the mean AChE versus controls, independent t-tests yielded (AChE) activity significantly lower in cancerous patients compared to controls (p-value range between 0.02 to 0.0001)." (PMID 38429330, 2024). "There is a clear relationship between low AChE activity and poor prognosis in cancer patients; however, it is relevant to figure out why a reduction in AChE activity and protein content induces tumor progression and aggressiveness." (PMID 37760598, 2023).